IL6 (interleukin 6)
Diseases named in the same sentence as IL6 in open-access papers (continued):
Sharing a sentence is not in itself a finding about the gene and the disease.
tumor (continued). "Serum IL-6 levels are significantly higher in patients with HCC than in healthy individuals and higher levels of IL-6 have been correlated with tumor mass and cancer invasiveness." (PMID 22470194, 2012). "Among soluble factors released from astrocytes, IL-6 was most likely responsible for tumor growth, because only the expression of IL-6R on tumor cells was up-regulated during the activation with astrocytes." (PMID 23271367, 2012). "Paradoxically, many of the proinflammatory cytokines induced after chemotherapy, particularly IL1β, IL6, and IFNα/β, can exert both tumor-inhibiting and tumor-promoting effects (double-edged sword)." (PMID 22400040, 2012). "Our present study also shows that intra-peritoneal administration of SP can dramatically elevate the expression of pro-inflammatory cytokines IL-6 and IL-11 in HeLa cell xenograft tumours." (PMID 22442729, 2012). "In tumor tissue, high levels of IL-6 (>3000 pg/100 mg tumor) were observed exclusively in imidazoquinoline-treated tumors, which on average had four times higher levels than placebo-treated tumors (P < 0.01)." (PMID 22481916, 2012). "Serum and tumor levels of proinflammatory cytokines, IL-6 and MCP-1, were assessed by ELISA 2 days and/or 9 days after treatment with imidazoquinoline." (PMID 22481916, 2012). "These were increases of (systemic) levels of tumor-derived protein Hsp72 (heat shock protein), and of inflammatory cytokines IL-6 and TNF-α." (PMID 23233905, 2012). "DCs in MM patients are a target of tumor-associated suppressive factors, such as IL-10, TGF-β, VEGF, and IL-6, resulting in their aberrant functions and impaired development of effector functions in tumor-specific lymphocytes." (PMID 22481968, 2012). "This immune dysregulation should be proved by altered IL-6/IL-10; iii) the decrease in IL-6 levels and increase in IL-10 levels are evidence of an altered host immune response to the tumour, confirmed by cell activation due to BCG." (PMID 23181118, 2012). "The broad importance of cytokines, especially IL-1 and IL-6 to tumor growth is relevant to sex disparity in brain metastases because astrocyte production of cytokines is sexually dimorphic." (PMID 22277186, 2012). "In those studies, cancer-derived IL-1a played a key role in inducing CAFs to release factors with functions in tumor migration and invasion (i.e., IL-1a, IL-8, IL-6, and others)." (PMID 23342263, 2012). "Interleukin-6 has been shown to increase the anti-apoptotic and oncogenic potential of tumour cells, as well as inducing drug resistance in vitro." (PMID 22433965, 2012). "IL-6 and TNF-α are the major pro-inflammatory cytokines implicated in inflammation-associated carcinogenesis, enhancing tumour cell growth." (PMID 23176085, 2012). "Glioma-derived tumor cells are capable of directly secreting immunosuppressive cytokines, including IL6, IL10, and TGF-β, and microglia and astrocytes have also been documented as sources of cytokines." (PMID 22312408, 2012). "These immune cells release pro-inflammatory molecules, such as TNF-α, IL-6, and IL-1α, which activate signaling pathways and promote tumor growth." (PMID 23272179, 2012). "Our previous study showed that R phase tumor infiltrating lymphocytes (TILs) produced large amounts of interleukin (IL)-6 which antagonized transforming growth factor (TGF)-β derived from CTVT to diminish the immune-suppressive microenvironment." (PMID 23136963, 2012). "Incubating bone marrow (BM) precursors with a combination of granulocyte-macrophage colony-stimulating factor (GM-CSF) and interleukin-6 (IL-6) generated a tumor-infiltrating MDSC-like population that impaired anti-tumor specific T-cell functions." (PMID 22762146, 2012). "Inhibition of NF-κB activity prevented NK cell depletion, and thus increased anti-tumor activity by decreasing IL-6 production." (PMID 22567084, 2012).
tumor (continued). "To further investigate the effect of hochuekkito in vivo, we examined expression of IL-6 in tumor tissues collected from C26-bearing mice treated with or without hochuekkito." (PMID 23326296, 2012). "In contrast to this, IL-6 has been shown to possess anti-tumor effects as in the example of treatment of B16 melanoma or small cell lung carcinoma." (PMID 22236378, 2012). "Both cytosolic and secretory forms of IL6 are found in cells and in tissue microenvironments, and IL6 can be produced by tumor cells as well as by some immune cells or normal tissues." (PMID 23185547, 2012). "Demonstration of the existence of IL-6-producing tumor cells would therefore require cultivation of tumor cells and measurement of their IL-6 activity, and will be the focus of a future study." (PMID 22713692, 2012). "Over-expression of MnSOD in MCF-7 cells have been reported to reduce transcriptional activity of the transcription factors AP-1 and NF-κB and decreased expression of interleukin IL-1 and IL-6, contributing towards tumor supression." (PMID 23153283, 2012). "Activation of MDSCs not only requires tumour-derived factors (e.g., tumour-derived prostaglandin E2 (PGE2)) but also IFN-γ produced by T cells and factors secreted by tumour stromal cells (like IL-1β, IL-4, IL-6, IL-10, IL-13)." (PMID 22778767, 2012). "In malignancy, increased serum levels of IL-6 correlates with the extent of tumor invasion, and metastasis." (PMID 23483792, 2012). "Immunosuppressive cytokines and growth factors known to be secreted directly by tumor cells include IL6, IL10, TGF-β, and VEGF." (PMID 22312408, 2012). "The association of cytokines such as interleukin 6 and VEGF, which was produced significantly more after open surgery, with tumor recurrence has been demonstrated in animal models." (PMID 22318646, 2012). "We have shown that the oncolytic vaccinia virus strain GLV-1h90 can be used to functionally express the designer cytokine hyper-IL-6 in human tumor xenografts of live mice." (PMID 22236378, 2012). "DCs found within tumour infiltrates are commonly “frozen” in an immature status (iDCs) by soluble factors of the tumour milieu such as IL-4, IL-6, GM-, and M-CSF." (PMID 22400028, 2012). "In cancer patients, high levels of circulating IL-6 were observed with almost every type of tumor and predicted a poor outcome." (PMID 23326296, 2012). "Microenvironment-derived interleukin promotion of tumor growth has also been seen with IL-1β stimulation of melanoma and IL-6 promotion of primary colon cancer and liver cancers." (PMID 22277186, 2012). "The role of cytokines can be either pro-inflammatory, tumor-promoting (interleukins IL-6, IL-12 family, IL-23) or tumor-inhibiting, as is the case of IL-10." (PMID 24710489, 2012). "Hyper-IL-6 was secreted from the infected tumor tissue into the circulatory system enabling it to induce systemic effects." (PMID 22236378, 2012). "Analysis of mechanisms underlying this effect revealed that IL-21 sustains CD4+ T cell infiltration in the tumor and peritumor areas and enhances the production of IL-6 and IL-17A as well as STAT3 activation." (PMID 23109839, 2012). "Proinflammatory factors such as nitric oxide, IL-6 and IL-12 were shown to be released from tumor cells in previous studies." (PMID 22815694, 2012). "The uptake of apoptotic tumor cells induced a massive production of IL-6 in both IFN-DC and IL-4-DC, while the production of IL-23 was selectively induced in IFN-DC." (PMID 21387004, 2011). "These two drugs, particularly when used in combination, promote tumor cell apoptosis and down-regulate the expression IL-6, IL-8, and TNF-α cytokines." (PMID 21345194, 2011). "IL-6 can be released from tumor infiltrating leukocytes, but is produced to a large extent by tumor cells themselves." (PMID 21546718, 2011). "Some researchers have suggested that Th17 cells promote tumor growth through an IL-6/STAT3 pathway, up-regulation of IL-8, and induction of tumor angiogenesis." (PMID 22051182, 2011).
tumor (continued). "The liberation of multiple proinflammatory cytokines, including interleukin-1 (IL-1), IL-6, and tumor necrosis factor-α from the tumor environment eventually results in the induction of CRP synthesis from the liver and other tissues." (PMID 22103888, 2011). "Despite the requirement for IL-6 in mediating the tumor promoting abilities of fibroblasts, we found that IL-6 alone was not sufficient for expansion of CD44+/CD24−/EpCAM+ cells in the MCF7 cell line." (PMID 21957456, 2011). "Pro-inflammatory cytokines, such as TNF and IL-6, can influence all stages of tumor development, including initiation, promotion, progression and metastasis." (PMID 21943068, 2011). "IL-6 is a critical tumor promoter regulated by activated transcription factor NF-κB and IL-6 gene amplification occurs in 40-50% of GBM patients." (PMID 21906308, 2011). "AKT-dependent IL-6/STAT3 activation was therefore suggested to be responsible for the tumor promoting effects of IL-17 on HCC." (PMID 22171994, 2011). "IL-6, produced either by infiltrating immune cells or tumor cells, not only provides survival signals to cancer cells but also facilitates motility of cancer cells through the EMT." (PMID 21559372, 2011). "Burger also reported that cancer cells and tumor-related macrophages can release high concentrations of IL-6." (PMID 21345194, 2011). "In this regard, it is interesting to point out that oncogenic Ras has been shown to induce IL-6 and IL-8, both of which are NF-κB-regulated genes and shown to promote Ras transformation and tumor growth." (PMID 21897875, 2011). "An immune response to the tumor resulting in activation of macrophages and the release of cytokines, such as tumor necrosis factor, IL-1, IL-6, and interferon-r, is central to the current model, as is the release of tumor by-products." (PMID 21896191, 2011). "Especially IL-6, correlating with tumor stage and lymph node status, has been proven to be an independent predictor of poor survival." (PMID 21264308, 2011). "IL-6 is produced from epithelial tumor cells themselves as well as stromal cells, and cancer-derived IL-6 induces a cancer stem cell-like phenotype in these cells." (PMID 21967801, 2011). "Tumor-derived factors, such as pro-inflammatory cytokines IL-6 and IL-1β, promote the formation of MDSCs resulting in their accumulation in the blood, lymphoid organs and tumor." (PMID 24212948, 2011). "IL-17 mediated tumor-promoting role involves a direct effect on HCC cells through IL-6/JAK2/STAT3 induction by activating the AKT pathway." (PMID 22171994, 2011). "IL-6, produced from bone marrow-derived cells, promotes growth of tumor-initiating cells during early tumorigenesis and protects these cells from apoptosis." (PMID 21967801, 2011). "We noted that IL-6 levels were significantly correlated with the tumour size with higher IL-6 levels was detected in tumours sized ≥ 5 cm (P = 0.001, r = 0.564)." (PMID 21294915, 2011). "Initial studies of mouse mAb to IL-6 (murine BE-4 and BE-8) demonstrated a transient tumor cytostasis and reduction in toxicities from IL-6." (PMID 22046572, 2011). "In neuroblastoma and multiple myeloma, IL-6 derived from stromal cells was shown to be an important mediator between cancer cells and the bone microenvironment by supporting tumour survival and affecting osteoclast differentiation, respectively." (PMID 22075946, 2011). "The cytokine IL-6 has been found to be a major contributor to the tumor microenvironment and many tumors have been found to express high levels of IL-6 or an IL-6 receptor." (PMID 21526200, 2011). "It has been indicated in this study that IL-6 level increases as the aggressive behaviour of the tumour increases (IL-6 levels increase as the stage of the cancer increases)." (PMID 21294915, 2011). "Many tumor cells have been found to produce excess amounts of IL-6 or alternatively, express an IL-6 receptor which allows them to respond to IL-6 produced by the tumor microenvironment." (PMID 21526200, 2011).
tumor (continued). "In vivo, AMT showed some antitumor activity in tumor xenograft models of colon and mammary cancer, and in immune stimulation via induction of IL-6 and tumor necrosis factor (TNF)-alpha in human peripheral blood mononuclear cell (PBMCs)." (PMID 21943068, 2011). "The pathogenesis of tumor cachexia is still not fully understood but a multifactorial process including pro-inflammatory cytokines like IL-6 or TNF-α, neuroendocrine hormones, downregulation of IGF-1 and tumor proteolysis inducing factor is assumed." (PMID 21892933, 2011). "One possibility is that elevated ascites IL-6 levels promote de novo tumor cells resistance to chemotherapy contributing to earlier disease recurrence." (PMID 21619709, 2011). "Most importantly, through its ability to up-regulate the expression of tumor promoting cytokines, such as IL-6 or TNF-α, and survival genes, such as Bcl-XL, NF-κB provides a critical link between inflammation and cancer." (PMID 21901145, 2011). "The link between inflammation and carcinogenesis is well known; experiments have implicated many components of the inflammatory cascade such as prostaglandin E2 and IL-6 as key players in tumor development, growth, and metastasis." (PMID 21481226, 2011). "As a confirmation, in murine B16 melanoma and MB49 bladder carcinoma, IL-17 mediated tumor-promoting role involves a direct effect on tumor cells through IL-6 induction and subsequent signal transducer and activator of transcription 3 (STAT3) activation." (PMID 22171994, 2011). "A number of studies on the in vitro differentiation of M2 macrophages - when monocytes or immature DC are exposed to tumor cell supernatant derived from lung, ovarian or cervical cancer cell lines - showed that this differentiation depended on IL-6." (PMID 22176642, 2011). "Although it did not quite reach statistical significance (P = 0.076), entering residual tumor > 2 cm in the multivariate model still showed that high IL-6 levels was significantly correlated with shorter progression-free survival." (PMID 21619709, 2011). "TB mice had elevated levels of the procachectic cytokines TNFα (77.2%greater than C; P=0.02) and IL-6 (8,120.1% greater than C;P=0.01) 14 days after tumor implantation." (PMID 21069263, 2011). "A second strategy to interfere with immune cells in the tumor micro milieu is the blockade of cytokines secreted by the tumor or immune cells (e.g. M-CSF or IL-6)." (PMID 22176642, 2011). "While other studies show that IL-17A can promote tumor growth and metastasis through IL-6/Stat3 signaling pathway or through the induction of tumor promoting microenvironment at tumor site." (PMID 21760911, 2011). "Serum levels of the IL-6 responsive acute phase reactants fibrinogen, haptoglobin and Von Willebrand Factor were also markedly induced in response to the tumor." (PMID 21799891, 2011). "The serum levels of IL-6 evidenced statistically significant differences with relation to changes in tumor size." (PMID 21294915, 2011). "Oncostatin M (OSM) is a member of the IL-6 cytokine family produced by inflammatory cells and some tumor cells including primary human osteoblasts and the human OSA cell line MG-63." (PMID 21481226, 2011). "Tumor necrosis factor-α and interleukin-6 release was clearly increased by DC incubated with H-1PV-induced SK29-Mel tumor cell lysates (TCL) and was also high with DC-CTL co-cultures incubated with H-1PV-induced TCL." (PMID 22029859, 2011). "Interleukin-6 (IL-6) was often reported to be present in tumor fluids and was a produced by many tumor derived cell lines." (PMID 22176642, 2011). "The murine model of cancer cachexia associated with systemic inflammation suggests that there is an interplay between IL-1 β and IL-6 within the tumour microenvironment, which leads to their amplification." (PMID 21760776, 2011). "STAT3 expression is often found in tumors and tumor-infiltrating macrophages and is induced by IL-6 and IL-10." (PMID 22176642, 2011).
tumor (continued). "Not only can Stat3 increase NFkB activity in tumors, but activation of Stat3 in immune cells in the tumor is dependent on NFkB and IL-6 which is downstream from NFkB." (PMID 20885960, 2010). "We therefore analyzed these tumor samples for IL-6 expression by immunohistochemistry and determined that control tumors expressed high levels of IL-6." (PMID 20929542, 2010). "This trend was also confirmed in the endothelial compartment of healthy and tumor tissues, with the comparison between IL-6+ cells in AC (6.8%) and healthy tissue (2.9%) being significant (p < 0.05)." (PMID 21059221, 2010). "The inflammatory cytokine interleukin (IL)-6, is part of an autocrine cytokine network that influences tumour growth." (PMID 20808314, 2010). "The genetic ablation of il6 diminishes tumour burden in ApcMin and in CAC-challenged wild-type mice, DEN-induced liver and in a tobacco smoke-associated lung cancer model." (PMID 20478049, 2010). "Long-term changes in levels of IL-8 and IL-6 after therapy are connected with tumor response to treatment and with tumor progress." (PMID 20184737, 2010). "Interleukin-6 (IL-6) binds both the membrane and soluble forms of the IL-6 receptor (sIL-6R), which induces a complex with gp130, and proliferation of tumour cells." (PMID 20823887, 2010). "A requirement for IL-6 signaling in tumor formation has been demonstrated by using IL-6 knock-down approaches as well as blocking antibodies to IL-6 in a variety of cell types." (PMID 20929542, 2010). "Nevertheless, we postulated that this would be a useful signature of the phenotype induced by IL-6 over-expression which has been experimentally shown to increase tumor growth in vivo." (PMID 21179572, 2010). "IL-6 is a potent inflammatory cytokine that is considered a key tumor-promoting and antiapoptotic factor." (PMID 20544025, 2010). "In contrast to that, addition of a neutralizing anti-IL-6 antibody completely abolished the stimulation of tumour cell invasion induced by fibroblasts in co-cultures." (PMID 20723242, 2010). "We previously demonstrated that AS2 cells produced autocrine IL-6 and the secreted IL-6 induced Stat3 activation and subsequently promoted tumor progression." (PMID 21122157, 2010). "In the present study, it was shown that expression of PCNA, MMP-9, VEGF, HGF and IL-6 in tumor tissues in groups I, II and III, which received incomplete RFA, increased remarkably." (PMID 20667141, 2010). "While there is ample evidence for IL6 in promoting tumour activity on epithelium, the role played by the other family members is less well defined." (PMID 20478049, 2010). "Interleukin-6, produced by the tumor or surrounding cells, stimulates liver production of acute-phase reaction proteins (such as C-reactive protein (CRP) and fibrinogen) in both the fasted and fed states." (PMID 21176210, 2010). "Treatment with the tyrosine kinase inhibitors Gleevec (imatinib) or PTK787/ZK 222584, siRNA-mediated knock down of Vascular Endothelial Growth Factor (VEGF) and/or IL6 potently inhibited tumour angiogenesis and growth in this model." (PMID 20202196, 2010). "In in vitro studies, the autocrine production of IL-6 by tumor cells increased the resistance to chemotherapy." (PMID 21209958, 2010). "Although IL-6 was expressed in the cytoplasm of the cancer cells, IL-6R was expressed in tumour cell membranes." (PMID 20823887, 2010). "IL-6 mRNA was found to be elevated in tumor tissue in gp130 mutant mice with abnormally activated Stat3." (PMID 21122157, 2010). "Expression of PCNA, MMP-9, VEGF, HGF and IL-6 in tumor tissues increased significantly in the RFA-treated groups compared with the control group, and of the increases were greatest in the 55°C group (P < 0.05)." (PMID 20667141, 2010). "Whereas blocking of IL-6 by a neutralising antibody showed that increased amounts of this cytokine was necessary for tumour cell invasion, indicating that a complex cytokine network is needed for stimulation of this process." (PMID 20723242, 2010).